KEAP1 (kelch like ECH associated protein 1)
Diseases named in the same sentence as KEAP1 in open-access papers (continued):
Sharing a sentence is not in itself a finding about the gene and the disease.
anemia (3 papers, 2017 to 2026). A reduction in the number of red blood cells, the amount of hemoglobin, and/or the volume of packed red blood cells. "We hypothesized that the increased anemia in the Keap1-KD mice was at least in part caused by the documented Nrf2-dependent transcription of bone morphogenetic protein 6 (Bmp6) in liver sinusoidal endothelial cells." (PMID 34526660, 2021). "Curiously, we found that anemia was more prevalent in Keap1-KD animals than in any of the other three genotypes (p < 0.001 for Keap1-KD vs. WT; p = 0.012 for Keap1-KD vs. Nrf2-KO; p = 0.005 for Keap1-KD vs. Nrf2-KO/Keap1-KD)." (PMID 34526660, 2021). "Another interesting observation from this study is the increased prevalence of anemia in Keap1-KD animals fed high-fat diet than in any of the other three genotypes." (PMID 34526660, 2021). "Anaemia, growth retardation and poor survival are not recapitulated in renal tubular-specific Keap1-deficient mice (Keap1-TKO), indicating that these phenotypes are independent of Nrf2 activation in the renal tubules." (PMID 28233855, 2017).
bacteremia (3 papers, 2013 to 2023). "In the mouse sepsis syndrome model, Keap1 deletion in macrophages resulted in reduced levels of inflammatory mediators, organ injury, bacteremia and mortality, whereas Nrf2 deletion had the opposite effects." (PMID 37723178, 2023).
carcinoid (3 papers, 2019 to 2022). "We demonstrated that in carcinoid cell lines, the KEAP1 silencing induces an upregulation of NRF2 and some of its targets and that there is a direct correlation between KEAP1 methylation and its mRNA levels." (PMID 31126053, 2019). "Despite the literature evidence, to exclude this possibility we analyzed all carcinoid cohorts, searching for somatic alterations in the whole coding region of the KEAP1 gene and in the Neh2 domain of the NFE2L2 gene." (PMID 31126053, 2019). "A clear modulation by KEAP1 on these NRF2-target proteins has been observed and confirms the control activity by KEAP1 protein to the detoxifying pathway NRF2-related in carcinoids cells." (PMID 31126053, 2019). "Finally, it must be take into account that NRF2 levels can be regulated in a KEAP1-indipendent way by carcinoid tumor-related oncogenes, so their profile should impact and must be monitored to predict a tumor response to pharmacological treatments." (PMID 31126053, 2019). "The impact of KEAP1 methylation on its transcriptional activity was also assessed by in vitro demethylating treatments in SCLC, carcinoid and NSCLC cells." (PMID 31159323, 2019). "We aim to investigate the effects of KEAP1 on NRF2 modulations and the existing molecular background of this pathway in low/intermediate grade lung NETs by evaluating the effects of KEAP1 silencing on NRF2 and its target activity in carcinoid cell lines." (PMID 31126053, 2019). "An inverse correlation between KEAP1 mRNA levels and methylation levels was demonstrated by in vitro 5′-azacytidine treatment on carcinoid, SCLC and ADC cells, thus corroborating the general idea that consensus sequences of several transcription sites was marked in the epigenetic control of KEAP1." (PMID 31159323, 2019).
cholestasis (3 papers, 2022 to 2026). Impairment of the bile flow caused by obstruction within the liver, or outside the liver in the bile duct system. "The deficiency of these metabolites, coupled with a direct suppression of the placental Nrf2/Keap1 antioxidant signaling pathway by cholestasis, leads to placental oxidative stress." (PMID 41938768, 2026). "Probably, the direct NRF2 contributions for enhanced Hmgcs1 expression in cholestasis livers are small, but there might be a KEAP1-dependent signaling effect." (PMID 38731931, 2024). "Furthermore, concurrent localization of carbonylated proteins in hepatocytes that accumulate p62 suggests that the mechanism of autophagy induction during cholestasis is in part due to Keap1-mediated activation of p62 even though Nrf2 is not activating all of its targets." (PMID 36378690, 2022).
colorectal tumors (3 papers, 2012 to 2024). "We performed statistical analyses to determine whether the KEAP1 methylation status of colorectal tumor samples is associated with the clinicopathological features of CRC patients." (PMID 22325485, 2012).
Friedreich ataxia (3 papers, 2024 to 2025). An inherited condition that affects the nervous system and causes movement problems. "It has been shown that KEAP1-Cys151 is the important sensor for the Class I group of electrophiles, including CDDO-Im, which is structural analogue of the recently approved Omaveloxolone for the treatment of Friedreich’s ataxia patients." (PMID 39307045, 2024).
hepatoblastoma (3 papers, 2015 to 2023). Hepatoblastoma (HB) is a malignant hepatic tumor and is the most common pediatric liver cancer. "Using the human hepatoblastoma cell line HepG2, we examined whether BU affected the Keap1–Nrf2 pathway." (PMID 37039781, 2023). "Therefore, we screened the lungs of 90-week-old Keap1:.Alb-Cre mice for hepatoblastoma manifestations." (PMID 36209041, 2022).
hydronephrosis (3 papers, 2016 to 2023). Collection of urine in the renal pelvis that results in dilatation of the renal pelvis and calyces. "Renal epithelial cell specific deletion of Keap1 in Ksp-Keap1-/- mice caused marked renal pelvic expansion and significant compression of medullary parenchyma consistent with hydronephrosis in both (3 month-old) males and females." (PMID 27484495, 2016). "Through the analysis of NEKO mice, we identified a novel phenotype in which Nrf2 hyperactivation mediated by the loss of Keap1 in the developing kidney causes NDI and hydronephrosis." (PMID 28233855, 2017). "Here we show that deletion of oesophageal Nrf2 in Keap1-null mice allows survival until adulthood, but the animals develop polyuria with low osmolality and bilateral hydronephrosis." (PMID 28233855, 2017). "These unexpected findings demonstrate that Keap1 deletion in renal tubular epithelial cells results in an abnormal kidney development consistent with hydronephrosis and reveals a novel Keap1 mediated signaling pathway in renal development." (PMID 27484495, 2016). "In summary, these data demonstrate that Keap1 may be involved in normal kidney development and that a defective Keap1 results in hydronephrosis." (PMID 27484495, 2016). "Kidneys from 6 month-old Ksp-Keap1-/- mice showed progressive hydronephrosis." (PMID 27484495, 2016). "In conclusion, our unexpected finding may suggest a novel role for Keap1 mediated signaling pathway in renal development and indicate that absence of Keap1 in renal tubular epithelial cells significantly affects normal kidney development leading to hydronephrosis." (PMID 27484495, 2016). "Hydronephrosis has not been previously reported in the Nrf2ꜛ mouse, but only in a mouse in which Keap1 was specifically deleted in the renal epithelium." (PMID 36979025, 2023). "This developmental stage-specific effect of dioxin (or window to dioxin) appears to be similar to our observation that Keap1-TKO mice develop hydronephrosis after DOX treatment during development but not in adulthood." (PMID 28233855, 2017). "Thus it is not until NEKO mice were generated that polyuria and hydronephrosis were identified as a consequence of constitutive Nrf2 activation by the complete knockout of Keap1." (PMID 28233855, 2017).
Hypercholesterolemia (3 papers, 2016 to 2024). An increased concentration of cholesterol in the blood. "Of note, a mild hypercholesterolemia has already been observed due to Keap1 deletion in WT mice and was attributed to a reduced expression of the Cyp7a1 (cytochrome P450 family 7 subfamily A member 1) gene, which encodes for an enzyme involved in the biotransformation of cholesterol into bile acids." (PMID 34298930, 2021). "Therefore, the phenotypical hypercholesterolemia detected through the dual disruption of Keap1 and Rbpjκ genes from hepatocytes is hypothesized to be due to effects through anomalous lipid metabolism during the time of lactation feeding of the postnatal pups." (PMID 38731931, 2024).
intervertebral disc degeneration (3 papers, 2021 to 2025). "Additionally, Quercetin has been reported as a promising therapeutic agent for intervertebral disc degeneration, potentially through binding to the Keap1-Nrf2 complex and suppressing the NF-κB pathway." (PMID 40917752, 2025).
iron deficiency (3 papers, 2018 to 2023). "In the case of the Nrf2 inhibitor Keap-1, iron deficiency elevated its protein level, while utilization of FKN at the higher concentration significantly decreased Keap-1 expression." (PMID 37175630, 2023). "In our previous study, it was revealed that FKN can modify the Nrf2 protein level, as well as its negative regulator, Keap-1, in iron deficiency, which may cooperate with the impact of iron availability on the level of FP, FTH and HO-1." (PMID 37373063, 2023). "Similar to the 24 h long treatments, in the case of the Nrf2 inhibitor Keap-1, iron deficiency elevated its protein level, while utilization of FKN at the higher concentration significantly decreased Keap-1 expression at 48 h." (PMID 37175630, 2023).
kidney cancer (3 papers, 2017 to 2022). Primary or metastatic malignant neoplasm involving the kidney. "Thus, we concluded that the orchestration of OTUD1 with KEAP1 functions to suppress kidney cancer in humans, and therefore, OTUD1 is a critical regulator to maintain homeostasis." (PMID 35941131, 2022).
liver cirrhosis (3 papers, 2022 to 2024). "One study showed that endogenous opioid levels increase with liver cirrhosis, a condition also associated with a significant increase in thrombospondin-1 (THBS-1) and Keap1, as well as a reduction in Nrf2." (PMID 38255895, 2024). "Newer methods addressing liver cirrhosis have focused on the dysfunction of the Nrf2/Keap1 pathway." (PMID 38255895, 2024). "If, as reported in patients with liver cirrhosis, the E3 ubiquitin ligase synoviolin (HRD1) is increased, leading to Nrf2 ubiquitylation and Keap1-independent Nrf2 degradation, then targeting HRD1 rather than Keap1 might be promising." (PMID 35740009, 2022).
liver failure (3 papers, 2014 to 2022). A liver disease characterized by the liver losing or has lost all of its function. "Persistent activation of Nrf2 due to sequestration of Keap1 into Sqstm1-positive structure causes hepatomegaly and liver failure in Atg7f/f;Albumin-Cre and Atg5f/f;Albumin-Cre mice." (PMID 26483381, 2015). "Previously, it was shown that Nrf2 deficiency in mice conferred susceptibility to ConA-induced liver failure and, on the other hand, amplification of Nrf2 effects by conditional deletion of Keap1 in hepatocytes (cKeap1 KO) protected against ConA-mediated inflammatory liver injury." (PMID 24997191, 2014). "In conclusion, our study provides evidence that miR-125b-5p can alleviate LPS/D-GalN-induced ALF by regulating the Keap1/Nrf2/HO-1 signaling pathway, and therefore, regulation of miR-125b-5p and its downstream target Keap1 may serve as an alternative intervention for liver failure." (PMID 36268033, 2022).
lung neuroendocrine tumors (3 papers, 2019 to 2022). "By contrast, the KEAP1 genetic alterations appear to be strongly related to a high-grade lung NET." (PMID 31126053, 2019).
memory impairment (3 papers, 2022 to 2024). "Opposite to the down-regulation of GSTA1, GSTO1, and KEAP1, the BACE1 and MAOA proteins are elevated during the aging-associated memory impairment." (PMID 35767571, 2022). "In the present study, we exogenously overexpressed P301S in cells and rodents to mimic Tau accumulation in FTDP‐17 patients and found that overexpressing P301S‐induced oxidative stress, synapse loss and memory impairments with significantly decreased NRF2 and increased KEAP1." (PMID 35917404, 2022).
mood disorder (3 papers, 2018 to 2024). A cognitive disorder a disturbance in which the person's mood is hypothesized to be the main underlying feature. "It was suggested that the Keap1-Nrf2 system plays a key role in the stress resilience, which is involved in the pathophysiology of mood disorders." (PMID 32380663, 2020). "In the review, the author would like to discuss the role of Keap1-Nrf2 system in mood disorders." (PMID 30386243, 2018).
Oral Cancer (3 papers, 2013 to 2020). "The Keap1-Nrf2 system plays a crucial role in cellular defense against oxidative stress, which has been reported to promote cancer development and resistance to chemotherapeutic drugs, but little is known about its association with carcinogenesis of oral cancer." (PMID 24386210, 2013). "However, further studies are needed to clarify the mechanism by which Keap1-Nrf2 system is involved in the development and progression of oral cancer." (PMID 24386210, 2013).
oral squamous cell carcinoma (3 papers, 2013 to 2026). "In HPV(−) oral cavity SCC (OSCC), we found NFE2L2(NRF2), KEAP1, and CUL3 genes were altered in 11%, 4%, and 4% of tumors, respectively." (PMID 38335300, 2024). "However, the role and clinical significance of oxidative stress markers Keap1 and Nrf2 in oral squamous cell carcinoma (OSCC) has not been elucidated." (PMID 24386210, 2013).
ovarian tumor (3 papers, 2014 to 2023). "DHT inhibits ovarian tumor growth by activating oxidative stress via Keap1-mediated Nrf2 ubiquitination and degradation." (PMID 37569328, 2023). "Interestingly, the same study noted 50% of tumors without KEAP1 mutations exhibited nuclear localization of NRF2 protein (denoting pathway activation), suggesting that other mechanisms are likely driving NRF2 pathway activation in ovarian tumors." (PMID 25114896, 2014).
polycystic ovary syndrome (3 papers, 2023 to 2025). A disorder that manifests as multiple cysts on the ovaries. "In this study, we aimed to evaluate glutathione status and the function of the Keap1-Nrf2 system in relation to anthropometric parameters and body composition in young women with polycystic ovary syndrome." (PMID 36978978, 2023).
sarcoma (3 papers, 2021 to 2025). A usually aggressive malignant neoplasm of the soft tissue or bone. "The results showed that high-level copy number gains of KEAP1 were observed in uterine carcinosarcoma, ovarian serous cystadenocarcinoma, and sarcoma." (PMID 35453346, 2022).
silicosis (3 papers, 2021 to 2025). Silicosis is a respiratory disease caused by breathing in (inhaling) silica dust. "Western blot analysis indicated that the Keap1 expression in silicosis mice was markedly reduced, while the expression of Nrf2 (p = 0.038, 95%CI = −0.96 to −0.03) was increased." (PMID 41561355, 2025). "The results of western bolt showed the protein expression of NRF2, KEAP1 and GCLM in PBMCs was higher in patients with silicosis than that of healthy controls." (PMID 34517882, 2021). "Moreover, RT-qPCR analysis showed that the expression of NRF2, KEAP1 and GCLM mRNA in PBMCs from patients with silicosis was higher than that in healthy controls." (PMID 34517882, 2021).
squamous non-small cell lung cancer (3 papers, 2015 to 2024). "Sapanisertib continues in limited clinical development, primarily focusing on patients with squamous non-small cell lung cancer with KEAP1/NRF2 (NFE2L2) mutations." (PMID 39510293, 2024). "Rare previous data from other carcinomas shows that in squamous non-small cell lung carcinoma Keap1 expression likewise associated with better survival with HR of 2.09." (PMID 25879528, 2015).
thyroid nodule (3 papers, 2016 to 2025). A small circumscribed mass in the THYROID GLAND that can be of neoplastic growth or non-neoplastic abnormality. "No other significant abnormalities were present in thyroid tissues, including driver gene mutations, although half the cases (2/4) had greater than 80% variant allele frequency of KEAP1, suggesting that the loss of heterozygosity of KEAP1 may be partially involved in forming the thyroid nodules." (PMID 39373520, 2025). "On the other hand, the presence of the R483H germline mutation in KEAP1 did not result in any nuclear accumulation of NRF2 in the non-nodular parenchyma of our patient, and no thyroid nodule was detected by ultrasonography in her 16-year-old son, who has same KEAP1 mutation as the patient." (PMID 27703446, 2016). "The thyroid tissue–specific phenotype also applies to Keap1 knockdown mice that develop diffuse goiter without thyroid nodules or hyperplasia." (PMID 39373520, 2025). "Intriguingly, constitutive activation of Nrf2 by knockdown of Keap1 leads to diffuse goiter with increased size of thyroid follicles and absence of thyroid nodules or hyperplasia, suggesting that an appropriate level of Nrf2 is required to maintain normal thyroid function and structure." (PMID 41002415, 2025).
tuberculosis (3 papers, 2019 to 2023). A chronic, recurrent infection caused by the bacterium Mycobacterium tuberculosis. "This work identified Keap1 alkylation as a new drug target for tuberculosis and provides a preliminary basis for the development of antituberculosis lead compounds based on JFD." (PMID 36819778, 2023). "This work identifies Keap1 alkylation as potential new drug target for tuberculosis and provides a preliminary basis for the development of antituberculosis lead compounds based on JFD." (PMID 36819778, 2023). "In total, the results indicate that the Keap1/Nrf2/ARE system can be an effective pharmacological target in host-adjunctive treatment of tuberculosis." (PMID 34093961, 2021). "The main purpose of our study is to establish ROS production during experimental tuberculosis in mice and to determine whether induction of the Keap1/Nrf2/ARE signaling pathway could affect granuloma formation." (PMID 34093961, 2021). "Our results suggest that the Keap1/Nrf2/ARE system could be a plausible and promising pharmacological target for tuberculosis treatment." (PMID 34093961, 2021).
type 1 diabetic nephropathy (3 papers, 2020 to 2022). "The beneficial effect of icariin in STZ-induced type 1 diabetic nephropathy seems to be causally related to the GPER-mediated p62-dependent Keap1 degradation and Nrf2 activation." (PMID 34248614, 2021). "Taken together, the present study demonstrated that the therapeutic effects of icariin on type 1 diabetic nephropathy in rats via GPER mediated p62-dependent Keap1 degradation and Nrf2 activation." (PMID 32766240, 2020).
acute pneumonia (2 papers, 2022 to 2025). "Kelch ECH-associating protein 1 (Keap1)-Nuclear factor erythroid 2-related factor 2 (Nrf2) axis is crucial for regulating oxidative stress and inflammatory responses in acute pneumonia." (PMID 40179791, 2025). "This study indicates that SA might be a new covalent molecule of Keap1 to activate Nrf2, and is a promising drug candidate or lead molecule for the therapy of acute pneumonia through regulating Nrf2/NF-κB/NLRP3 inflammasome axis." (PMID 40179791, 2025). "Our data indicated that SA significantly inhibited LPS-induced acute pneumonia in mice via up-regulating Nrf2, inhibiting NLRP3 inflammasome and NF-κB activation, and identified Keap1 as the direct target of SA." (PMID 40179791, 2025).
adenoid cystic carcinoma (2 papers, 2022 to 2025). A malignant tumor arising from the epithelial cells. "On the other hand, the Nrf2/Keap1 (nuclear factor erythroid 2-related factor 2/Kelch-like ECH-associated protein 1) signaling pathway was found to be influenced in adenoid cystic carcinoma (ACC) by MG-132." (PMID 40243672, 2025).